BRAF (B-Raf proto-oncogene, serine/threonine kinase)
Diseases named in the same sentence as BRAF in open-access papers (continued):
Sharing a sentence is not in itself a finding about the gene and the disease.
papillary thyroid carcinoma (continued). "In this study, BRAF V600E mutation was associated with aggressive disease in small papillary thyroid carcinoma ≤ 1.5 cm and papillary thyroid microcarcinoma ≤ 1 cm, defined by: ETE, LNM, and high-risk histological variants (tall cell, columnar, solid/trabecular, diffuse sclerosing)." (PMID 34742355, 2021). "In our group of 30 papillary carcinoma cases, DNA could be extracted from 29 and only nine expressed the BRAF V600E mutation." (PMID 34345541, 2021). "The study supported the risk stratification of papillary thyroid carcinomas into three subgroups based on BRAF V600E and TERT promoter mutation positivity, with increasing aggressiveness from dual negativity, positivity in either mutation alone, to dual positivity." (PMID 34702207, 2021). "Moreover, diverse papillary thyroid cancer cell lines harboring RET/PTC rearrangements or BRAF V600E mutation had higher osteopontin expression in comparison to normal thyroid cells." (PMID 34680488, 2021). "Type 1 is composed of BRAF V600E mutated tumors likely evolved from papillary thyroid carcinoma." (PMID 33543394, 2021). "Methylation of PHKG2 may be associated with mutation of the BRAF/RAS oncogene in papillary thyroid cancer." (PMID 34170849, 2021). "Only 14 cases were positive for the BRAF mutation; of these, nine were of papillary carcinoma." (PMID 34345541, 2021). "Although papillary thyroid cancers are known to have a relatively low risk of recurrence, several factors are associated with a higher risk of recurrence, such as extrathyroidal extension, nodal metastasis, and BRAF gene mutation." (PMID 34678881, 2021). "BRAF V600E mutated papillary carcinomas have distinct morphologic characteristics." (PMID 34934597, 2021). "Both papillary thyroid carcinoma and right colon cancer are characterized by BRAF V600E mutation, which might interact with TERT expression and TERT mutation for the promotion of tumour invasion." (PMID 32596958, 2020). "For instance, discovery of the oncogenic BRAF V600E mutation in high frequency (50–70%) in papillary thyroid cancers and its associated implication for susceptibility to BRAF targeted therapies have dramatically shifted the landscape of papillary thyroid cancer treatment." (PMID 33162941, 2020). "In some prospective studies published to date on the analysis of BRAF V600E mutation in patients with papillary thyroid carcinoma, the determination of the mutation was largely undertaken at the time of the total thyroidectomy surgical act or with the surgical reintervention for tumor relapse." (PMID 32575591, 2020). "In papillary thyroid cancer, RNA sequencing studies revealed that the presence of BRAF mutation is associated with a reduced expression of immune/inflammatory response genes as compared with wild type-BRAF tumors." (PMID 31762942, 2019). "Moreover, target gene MAPK1 was modified by DNA methylation to promote PTC cell cycle, proliferation, and migration, and the mutation of protein BRAF was revealed in papillary thyroid cancer at the Cosmic database." (PMID 31126066, 2019). "We aimed to investigate the prevalence of the BRAF (V600E) mutation in consecutive cases of papillary thyroid carcinoma (PTC) in patients diagnosed and treated at the Hospital Sao Rafael (Salvador, BA, Brazil) and evaluate its association with clinical and pathological characteristics of PTC." (PMID 30916170, 2019). "Mutations of RET, RAS or BRAF are present in approximately 70% of papillary thyroid cancers." (PMID 31200667, 2019). "The detection of BRAF Mutation is an important diagnostic tool for papillary thyroid cancer." (PMID 31841566, 2019). "The BRAF V600E mutation is highly specific for papillary thyroid carcinoma (PTC)." (PMID 29132392, 2017). "BRAF V600E mutation analysis may be a useful adjunct technique for confirming the diagnosis of papillary thyroid carcinoma." (PMID 29132392, 2017). "BRAF mutations were detected in 23 cases with papillary thyroid cancer (43%)." (PMID 28493027, 2017).
papillary thyroid carcinoma (continued). "B-CPAP is a papillary thyroid carcinoma cell line that is known to have BRAF V600E mutation." (PMID 27057371, 2016). "BRAF is the most frequently mutated gene in differentiated thyroid cancer (DTC)." (PMID 27387551, 2016). "It should be borne in mind that BRAF gene mutation, besides genetic and racial factors, seems to be influenced by the geographic area, as is testified by the percentage of papillary carcinomas in the population studied, and appears to be correlated with the amount of iodine in the diet." (PMID 26693224, 2015). "The BRAF mutation occurs commonly in papillary thyroid carcinoma (PTC)." (PMID 25712893, 2015). "In conclusion, in agreement with the literature data, the data from our population suggest that the presence of the BRAF V600E mutation should determine a more aggressive surgical approach (currently adopted only in cases of papillary carcinoma on final histology)." (PMID 26693224, 2015). "BRAF mutation was identified in the cancerous part of 31 (78%) papillary thyroid cancers." (PMID 24559116, 2014). "For example, in the study investigating the sensitivity of immunohistochemistry (IHC) versus Sanger sequencing to BRAF V600E mutations in FFPE derived DNA from papillary thyroid carcinoma specimens, Bullock and colleagues utilised the TSACP as an alternative sequencing platform." (PMID 24885028, 2014). "About 78% of the papillary thyroid cancers harbored the BRAF mutation." (PMID 24559116, 2014). "In our study, about 78% of papillary thyroid cancer harbored the BRAF mutation." (PMID 24559116, 2014). "CMV infection may activate the mitogen-activated protein kinase pathway, of which aberrant activation is frequently associated with BRAF mutation in papillary thyroid cancer." (PMID 24559116, 2014). "There might be subsets of papillary thyroid cancer hardly methylated and preferentially methylated, and aberrant methylation of these genes correlates a priori to BRAF/RAS oncogene mutation in papillary thyroid cancer." (PMID 24367375, 2013). "Nambaet al pointed out the link between BRAF mutation and papillary thyroid carcinoma." (PMID 23815863, 2013). "Oncogenic mutations of BRAF are the most common genetic events in melanomas and papillary thyroid cancers (PTC), and are thought to be involved in early stages of tumor development, as they are present in benign nevi and micropapillary thyroid cancers, respectively." (PMID 23372702, 2013). "Our group also found in papillary thyroid carcinoma (that also presents frequent mutation in BRAF gene) an increased activation of mTOR pathway in BRAF mutated PTC, and in vitro transfection of BRAFV 600E disclosed a positive association between BRAF (over)expression and mTOR pathway activation." (PMID 23904987, 2013). "BRAF mutations are the most prevalent genetic abnormality reported in papillary thyroid carcinoma." (PMID 23815863, 2013). "The high prevalence of BRAFV600E mutation in ATC supports the hypothesis that many ATCs actually represent a progressive malignant degeneration of BRAF-mutated, well-differentiated thyroid carcinomas." (PMID 24267151, 2013). "BRAF V600E mutation is typically found in papillary carcinomas with classical histology and in the tall cell variant, and is less common in the follicular variant of papillary carcinoma." (PMID 22654559, 2011). "Moreover, recently it has been shown that BRAF mutation in papillary thyroid cancer is associated with a more aggressive phenotype and less differentiated state due to decreased expression of iodide-metabolizing and sodium iodide symporter genes." (PMID 20628483, 2010). "These genetic signatures support the theory that sporadic papillary thyroid cancers originate via mutations in the RET/RAS/BRAF/MAPK pathway, and could also predict tumors with these mutations with high accuracy." (PMID 24281099, 2010).
papillary thyroid carcinoma (continued). "The T1799A mutation of the BRAF gene, affects up to 69 percent of papillary thyroid cancers." (PMID 21048836, 2010). "7q34 duplication in JPA was recently shown to produce novel oncogenic BRAF fusion genes with transforming capacity, similar to findings in radiation-associated papillary thyroid cancer where an intrachromosomal inversion, and not duplication, let to this oncogenic event." (PMID 19603027, 2009). "BRAF mutation has previously been shown to induce chromosome instability and decrease cell- cell interactions and our data further corroborates the involvement of these processes in papillary thyroid carcinoma." (PMID 17355635, 2007). "The most common genetic abnormalities associated with papillary thyroid carcinomas (PTCs) are activating mutations in BRAF, the gene for the B-type serine-thereonine kinase RAF, identified from 29 to 83% of patients, and RET/PTC rearrangements detected much less frequently in adult PTCs." (PMID 17667921, 2007). "Notably, BRAF V600E mutations are the most prevalent and significant, accounting for 98∼99% of all the BRAF mutations, which occur in approximately 40∼70% of papillary thyroid cancer (PTC) and 30∼40% of anaplastic thyroid cancer, especially in Chinese patients." (PMID 40586006, 2025). "Therefore, we evaluated whether the presence of BRAF mutation is associated with features of poor prognosis in 85 patients with papillary thyroid carcinoma older than 45 years treated at A.C. Camargo Cancer Center, from 1980 to 2007." (PMID 32972866, 2022). "The identification of BRAF p.V600E only in psammoma body samples surrounding BRAF p.V600E mutated papillary carcinoma is coherent with the hypothesis that the psammoma bodies in PTC originate indeed from dead papillary carcinoma cells." (PMID 32059434, 2020). "The presence of RAS mutations may contribute supportive evidence favoring a diagnosis of NIFTP, follicular adenoma, or follicular carcinoma, in contrast to BRAF mutations which are more commonly observed in association with classical papillary thyroid carcinoma." (PMID 28280647, 2017). "Thus, PLX4032 halts DNA synthesis selectively in the BRAF-mutated papillary thyroid cancer cells." (PMID 24673746, 2014). "However BRAF mutation occurs in approximately half of papillary thyroid cancers." (PMID 24386625, 2013). "Association of BRAF mutation with occult central neck lymph node metastases might support use of BRAF mutation as an indication for prophylactic central neck dissection for patients with conventionally low- to intermediate-risk papillary thyroid cancer." (PMID 24367375, 2013). "It is noted that in this hypothesis, the role of BRAF mutation is the prevention of immature fetal thyroid cells, namely thyroblasts that are the origins of papillary carcinomas, from differentiating into follicle-forming cells, such as follicular tumour cells or thyrocytes." (PMID 17453004, 2007). "Regarding BRAF, its prevalence ranges from 46% to 90% among papillary thyroid carcinomas (PTCs) identified on cytology." (PMID 41595518, 2026). "ddPCR identified five low-abundance BRAF p.V600E mutations (VAF 0.37–2.96%) that were missed by ARMS-PCR, one of which was confirmed as papillary thyroid carcinoma on postoperative pathology." (PMID 41862948, 2026). "Together, this evidence indicates that coexisting BRAF V600E and TERT promoter mutations synergistically drive tumor progression and enhance malignant behavior in papillary thyroid carcinoma." (PMID 40469184, 2025). "BRAF mutations are strongly linked to malignant transformation, whereas NRAS mutations are more commonly associated with the follicular variant of papillary thyroid cancer." (PMID 41356641, 2025). "Both dabrafenib and vemurafenib have been evaluated as single-agent BRAF inhibitors in patients with advanced, radioiodine refractory papillary thyroid cancer." (PMID 40869231, 2025).
papillary thyroid carcinoma (continued). "In our case, the genomic profiling of papillary thyroid carcinoma led us to identify a TRIM24::BRAF fusion." (PMID 40362680, 2025). "While BRAF V600E was selected in this study as a proof-of-concept marker due to its high specificity for papillary thyroid carcinoma, CytoMatrix has the potential to support more comprehensive molecular testing strategies beyond single-gene analysis." (PMID 41303583, 2025). "Genomic profiling of the papillary thyroid carcinoma identified a TRIM24::BRAF fusion with a read count of 2221." (PMID 40362680, 2025). "This study, based on 667 patients with papillary thyroid carcinoma (PTC), integrated BRAF V600E mutation abundance with clinical data and developed multiple machine learning models to predict the risk of cervical lymph node metastasis (CLNM)." (PMID 41228353, 2025). "BRAF V600E, the most common oncogenic driver in papillary thyroid carcinoma, activates the MAPK pathway and suppresses genes involved in iodine metabolism and differentiation." (PMID 41368991, 2025). "Genes less commonly rearranged in papillary carcinoma with BRAF V600E-like signature include BRAF, MET and ROS1 (e.g., CUL1-BRAF, MKRN1-BRAF, SND1-BRAF, TTYH3-BRAF CCDC30-ROS1 EML4-MET, and TFG-MET)." (PMID 41175860, 2025). "In most tumors of follicular cell origin, the primary molecular events are RAS or RAS-like (follicular-patterned tumors) and BRAF p.V600E or BRAF V600E-like (conventional papillary carcinomas) alterations." (PMID 41175860, 2025). "In summary, this rare case of concomitant BRAF V600E‐mutated NSCLC and pleural metastasis of papillary thyroid carcinoma demonstrates the effectiveness of targeted therapy with dabrafenib and trametinib." (PMID 39950095, 2025). "In addition, the lncRNA FAM111A-DT is also upregulated in papillary thyroid cancer and has been linked to BRAF^V600E oncogenic mutation, suggesting that specific lncRNAs may be linked with a specific oncogenic mutation, which may be correlated with more aggressive tumor behavior." (PMID 41154428, 2025). "BRAF V600E and telomerase reverse transcriptase (TERT) promoter mutations synergistically drive recurrence and mortality in papillary thyroid cancer." (PMID 40988283, 2025). "In another in vitro experiment, combining the HER inhibitor lapatinib with BRAF/MEK inhibitors dabrafenib/selumetinib significantly enhanced redifferentiation in BRAFV600E-mutant papillary thyroid cancer cells compared to BRAF/MEK inhibition alone." (PMID 40067410, 2025). "Here, we report a rare case of concomitant BRAF V600E‐mutated NSCLC and pleural metastasis from papillary thyroid carcinoma." (PMID 39950095, 2025). "BRAF p.V600E or equivalent molecular alterations (BRAF V600E-like signature) are the 'early/driver' events in the development of conventional papillary carcinoma." (PMID 41175860, 2025). "BRAF V600E analysis was selected as a proof-of-concept marker because of its well-established role in papillary thyroid carcinoma, the most common form of thyroid malignancy." (PMID 41303583, 2025). "This formed the basis of our Oncogenic Signature Of Papillary Thyroid Carcinoma Classification (OSPTCC), defining three subtypes: Inflammation-associated (IPTCC), BRAF/autophagy-related (BAPTCC), and lipid metabolism-related (LPTCC)." (PMID 40650680, 2025). "Recently, somatic cell-based BRAF gene testing was performed on the papillary carcinoma region, and somatic cell-based RET gene testing was conducted on the medullary carcinoma region." (PMID 41323380, 2025). "This study was designed with the aim of examining the relationship between clinicopathological characteristics and mutations in the BRAF, HRAS, KRAS, and NRAS genes with metastatic disease and RAIR development in patients with differentiated thyroid cancer." (PMID 40104288, 2025). "Contrarily, most of the DHGT are driven by BRAF V600E because they primarily exhibit papillary carcinoma-like cytoarchitecture." (PMID 38737660, 2024).
papillary thyroid carcinoma (continued). "Even in smaller-size papillary thyroid cancer cases of <1.5 cm, a significantly higher percentage of BRAF V600E cases demonstrate aggressive features such as extrathyroidal extension and lymph node metastasis compared to non-mutated cases." (PMID 38539437, 2024). "Patients with papillary thyroid carcinoma (PTC) and the BRAF mutation showed higher mean thyroglobulin levels (45.2 ± 22.5 ng/mL) compared to those without the mutation (28.5 ± 14.0 ng/mL), suggesting more intense tumor activity or a larger tumor mass." (PMID 39767732, 2024). "The predictive value of allele frequency (AF) of BRAF V600E and TERT mutations in papillary thyroid carcinoma (PTC) remains controversial." (PMID 38607456, 2024). "Our results show that BRAF-positive papillary thyroid cancer (PTC) patients tend to have older age, smaller tumor size, less vascular invasion, more frequent tumor multifocality, and a significantly higher cervical lymph node metastatic rate." (PMID 39235852, 2024). "Several studies have suggested the prognostic importance of the co-existence of BRAF p.V600E and TERT promoter mutations in differentiated thyroid cancer." (PMID 38672067, 2024). "The most common molecular alterations in papillary thyroid carcinomas are BRAF (62%)—predominantly, BRAFV600E—RAS (13%), RET-PTC (7%), and TERT promoter mutation (9%)." (PMID 36980552, 2023). "Genetic alterations in SCC include early and late molecular events, with early driver events mainly being RAS and BRAF mutations and RAS mutations associated with papillary carcinoma progression to hypo-fractionated carcinoma." (PMID 38303977, 2023). "We analyzed the association of mTOR expression with papillary thyroid cancer clinicopathological features, such as the TNM stage, BRAF V600E mutation, sex distribution, lymph node and distant metastases, and survival prognosis." (PMID 36980552, 2023). "Our study was also in keeping with other studies in the literature that showed poor clinicopathological outcomes for papillary thyroid cancer with concurrent TERT and BRAF V600E mutations." (PMID 36672362, 2023). "No genetic mutations relating to the occurrence of the solid variant of papillary thyroid carcinoma, including RET/PTC rearrangements and mutations in the BRAF or RAS, were detected by a gene panel test, namely, the OncomineTM Dx Target test." (PMID 38023212, 2023). "BRAF (predominantly BRAFV600E) is the most common molecular alterations in papillary thyroid carcinoma." (PMID 37446128, 2023). "We assessed the influence of Hashimoto’s thyroiditis and its influence on recurrence in patients with BRAF-wild type and BRAF-mutant differentiated thyroid carcinoma." (PMID 37190300, 2023). "The BRAF V600E mutation is the most common genetic variant in papillary thyroid cancer (PTC), but the relationship between the BRAF V600E mutation in PTC and cervical lymph node metastasis (LNM) remains controversial." (PMID 35784548, 2022). "Its mutation rate can be as high as 80% in papillary thyroid carcinoma (PTC), but BRAF mutations are rarely seen in benign nodules." (PMID 36160023, 2022). "Our study demonstrates that BRAF V600E IHC is more common among malignant tumors, especially in papillary thyroid carcinoma than in other tumors." (PMID 35646190, 2022). "Our results showed the effect of a BRAF mutation on VEGF-A secretion, as previously shown in other tumors such as papillary thyroid cancer." (PMID 35267541, 2022). "BRAF V600E was found in 70% of the papillary thyroid cancers, and AhR-interacting protein (AIP) was expressed more in papillary thyroid cancers particularly carrying BRAF mutations than in normal tissue, irrespective of acromegaly activity." (PMID 37435457, 2022).